MGP (matrix Gla protein)
Description:
Associates with the organic matrix of bone and cartilage. Thought to act as an inhibitor of bone formation.
Synonyms: MGLAP; GIG36; NTI
Tractability: Antibody: its Gene Ontology location is reachable by antibodies, with high confidence; UniProt places it where antibodies can reach, with medium confidence; UniProt predicts a signal peptide or a membrane-spanning region.
Gene: Protein-coding gene on chromosome 12 (14,880,864 to 14,887,639, reverse strand). Ensembl gene ENSG00000111341.
Subcellular location: Secreted
Gene Ontology:
Molecular function: protein binding; extracellular matrix structural constituent; structural constituent of bone; calcium ion binding
Biological process: cartilage condensation; ossification; regulation of bone mineralization; system development
Cellular component: extracellular exosome; extracellular matrix; non-collagenous component of interstitial matrix; extracellular region
Genetic constraint (gnomAD): Loss-of-function variants: 9 observed, 9.41 expected, observed/expected ratio (o/e) 0.96, 90% interval 0.57 to 1.63. That is too few expected variants to judge how well the gene tolerates losing a copy. Missense variants: 86 observed, 92.31 expected, observed/expected ratio (o/e) 0.93, 90% interval 0.78 to 1.12. Synonymous variants: 33 observed, 35.91 expected, observed/expected ratio (o/e) 0.92, 90% interval 0.7 to 1.23.
Gene-disease validity (ClinGen):
ClinGen rates the evidence that MGP causes each of these diseases.
Keutel syndrome (autosomal recessive): Definitive. Keutel syndrome is characterized by diffuse cartilage calcification, brachytelephalangism, peripheral pulmonary artery stenoses and facial dysmorphism.
Homologues: Orthologues: chimpanzee MGP (98% identical), macaque MGP (94% identical), dog MGP (86% identical), mouse Mgp (83% identical), pig MGP (83% identical), guinea pig MGP (82% identical), rat Mgp (81% identical), rabbit MGP (80% identical), tropical clawed frog mgp (53% identical), zebrafish mgp (28% identical).
Diseases named in the same sentence as MGP in open-access papers:
MGP is named in the same sentence as 176 diseases in open-access papers, as found by Europe PMC text mining. Sharing a sentence is not in itself a finding about the gene and the disease. The quoted sentences say what the papers report.
atherosclerosis (31 papers, 2007 to 2025). A disease characterized by the build-up of fatty material and calcium deposition in the arterial wall resulting in partial or complete occlusion of the arterial lumen. "Among these proteins, the deficiency of MGP was linked to arterial stiffness and vascular calcification, and Gas6's inadequate activity is suggested to lead to atherosclerosis." (PMID 40718363, 2025). "Among the 526 upregulated DEGs, were several well‐established genes associated with atherosclerosis plaques, such as matrix Gla protein, VIM, and B2M (Fig EV4D)." (PMID 38031960, 2023). "As MGP has such a central role in calcification, one can quickly realize why its inhibition by warfarin can eventually cause atherosclerosis." (PMID 33807457, 2021). "As warfarin inhibits the activity of MGP, it can cause dysregulation of apoptosis in vascular smooth muscle, which can lead to vascular smooth muscle proliferation and eventually vascular calcification and atherosclerosis." (PMID 33807457, 2021). "In addition, MGP knockout mice and rats develop medialrather than intimal calcification, which characterizes atherosclerosis.Therefore, a combined role of MGP deficiency with other factors has beensuggested." (PMID 18320012, 2007). "In cardiovascular health, it activates matrix Gla protein (MGP), which inhibits vascular calcification and reduces arterial stiffness and atherosclerosis." (PMID 40718363, 2025). "In the present study we investigated the role of single nucleotide polymorphisms (SNPs) of the matrix gamma-carboxy glutamic acid protein (MGP) on atherosclerosis progression and CVE in a CKD cohort." (PMID 38186884, 2024). "In atherosclerotic mouse models, MGP overexpression ameliorates atherosclerosis and arterial calcification, suggesting that active MGP protects against vascular injury." (PMID 39086959, 2022). "The study was planned to investigate the relationship of serum OPG, MGP and fetuin-A levels with the development of atherosclerosis in the stage 2–3–4–5 chronic kidney disease (CKD) patients who did not require dialysis treatment." (PMID 34583616, 2021). "Macrophages, key players in the atherosclerosis process, release matrix vesicles supplying a nidus for mineralisation within the plaque, and downregulate matrix Gla-protein (MGP) expression." (PMID 30717151, 2019). "Overexpression of MGP in the apoE−/− mouse model of atherosclerosis reduced both intimal and medial calcification of atherosclerotic plaques whereas gene deletion of MGP in apoE−/− mice accelerated intimal calcification of plaques." (PMID 22952653, 2012). "Several studies have suggested that consuming vitamin K2 analog supplements may help to delay the progression of atherosclerosis and improve the flexibility of arteries by promoting the activation of MGP to decrease calcification." (PMID 39851476, 2025). "Matrix Gla protein (MGP) is a calcium-binding matrix protein that is synthesized mainly in bone, cartilage and other tissues and is closely related to osteogenic differentiation, atherosclerosis and vascular calcification." (PMID 40216750, 2025). "Elevated dp-ucMGP has been previously reported in patients with atherosclerosis, and might reflect an increased production and release of MGP to counteract the atherogenesis." (PMID 29303985, 2018). "In women with osteoporosis and atherosclerosis, serum MGP and OC are also elevated." (PMID 27149062, 2016). "This may be due to the role of CD40 in thrombosis and inflammation, while MGP gene might have a protective role in atherosclerosis." (PMID 22135769, 2011). "However, serum MGP levels have been found to be significantly increased in patients with severe atherosclerosis and circulating MGP can be regarded as a marker of atherosclerosis reflecting the degree of inhibition of ongoing calcification processes in the vascular wall." (PMID 21143859, 2010).
atherosclerosis (continued). "We aimed to investigate the factors affecting the development of atherosclerosis and the role of calcification inhibitors fetuin-A, matrix-Gla protein (MGP), osteoprotegerin (OPG) in atherosclerosis progress." (PMID 34583616, 2021). "We aimed to investigate the factors affecting the development of atherosclerosis and the role of calcification inhibitors fetuin-A, MGP and OPG in atherosclerosis progress." (PMID 34583616, 2021). "On the other hand, contradictions related to the levels of OPG and MGP in CKD and their role in the development of atherosclerosis continue." (PMID 34583616, 2021). "On the other hand, MGP overexpression suppresses vascular BMP activity, atherosclerosis, intimal and medial calcification, and inflammation, in an atherosclerosis MGP transgenic mouse model." (PMID 32294899, 2020). "Matrix GLA protein (MGP), an inhibitor of medial calcification of arteries, is increased in patients with atherosclerosis." (PMID 21143859, 2010). "Upregulated genes in BBA-derived VSMCs are related to arterial mineralization and atherosclerosis, such as PTX3, SPP1, LOX, etc., whereas vasodilation and physiological regulatory genes such as MGP, ACTA2, and MYL9 were conversely enriched in conventional IA-derived VSMCs." (PMID 35874788, 2022).
Keutel syndrome (31 papers, 2009 to 2025). "Mutations of the MGP gene cause Keutel syndrome characterized by a complex phenotype, including extensive arterial calcification, as clearly shown in Mgp−/− mice that die before 2 months of age, exhibiting pronounced vascular calcification." (PMID 40926897, 2025). "Mutations in the MGP gene were found to be responsible for the Keutel syndrome, a condition characterized by abnormal calcifications in the cartilage, lungs, brain, and vascular system." (PMID 39684309, 2024). "The MGP function was clarified through the identification of mutations in MGP that lead to the Keutel syndrome." (PMID 39684309, 2024). "MGP deficiency causes Keutel syndrome, an extremely rare autosomal recessive disorder that is faithfully replicated in Mgp−/− mice." (PMID 38392293, 2024). "Mutations of the gene encoding human MGP cause Keutel syndrome, and MGP-null mice exhibit spontaneous artery and cartilage calcification." (PMID 38392329, 2024). "Biallelic loss-of-function variants in the MGP gene cause Keutel syndrome, an autosomal recessive disorder characterized by widespread calcification of various cartilaginous tissues and skeletal and vascular anomalies." (PMID 37923733, 2023). "Overall, our findings support that heterozygous variants in MGP altering the Cys19 residue cause autosomal dominant spondyloepiphyseal dysplasia, a condition distinct from Keutel syndrome both clinically and molecularly." (PMID 37923733, 2023). "Biallelic loss-of-function variants in the gene encoding Matrix Gla Protein (MGP) are known to cause a recessive disorder called Keutel syndrome." (PMID 37923733, 2023). "Consistently, arterial calcification is detected in some of patients with Keutel syndromes where loss-of-function mutations in the MGP gene are identified." (PMID 39086959, 2022). "The importance of MGP function has been elucidated in humans with the identification of mutations in MGP which is associated with an autosomal recessive disorder called Keutel syndrome." (PMID 35054981, 2022). "Due to the emerging knowledge on MGP and the association of loss-of-function mutations with Keutel syndrome, it was anticipated that undercarboxylated MGP is the major determinant in the development of skeletal defects in VKCFD1 patients." (PMID 35054981, 2022). "In this context, we highlight that permanent skin rashes were reported as a characteristic of the Keutel syndrome, and mutations in the MGP gene were reported as a crucial factor in this syndrome." (PMID 32974353, 2020). "This animal model resembles the human Keutel syndrome which is caused by a mutation in the MGP gene, which impairs carboxylation of MGP thereby inducing intimal and medial calcification." (PMID 30805347, 2019). "The fact that mutation in the gene encoding MGP causes Keutel syndrome, a rare autosomal recessive disorder characterized by severe soft tissue calcification, also suggests a pivotal role of MGP in VC prevention." (PMID 30717170, 2019). "In humans, homozygous mutations in the MGP gene cause Keutel syndrome, which is characterized by abnormal cartilage calcification, peripheral pulmonary stenosis, and midfacial hypoplasia." (PMID 31052252, 2019). "Keutel syndrome arises from MGP mutations and manifests as vascular calcification with skeletal abnormalities, and an MGP-deficient mouse model displays a similar phenotype." (PMID 31215457, 2019). "MGP is known as a potent inhibitor of vascular calcification, and mutation of MGP has been linked to Keutel syndrome, which is characterized by abnormal calcium deposition in peripheral stenosis of the pulmonary artery." (PMID 28298363, 2017). "In humans, nonsense mutations in MGP cause Keutel syndrome, a rare autosomal recessive disorder characterized by abnormal cartilage calcification." (PMID 28821877, 2017). "Mutations in human MGP that prevent synthesis of functional MGP suffer from Keutel syndrome, with excessive calcification of cartilage and pulmonary artery stenosis." (PMID 25210519, 2014).
Keutel syndrome (continued). "Keutel's syndrome is caused by a mutation in the gene encoding MGP, which is considered to be the most important inhibitor of vascular calcification." (PMID 23248645, 2012). "MGP is traditionally considered to be involved in the inhibition of calcification of arteries and cartilage, and germline mutations in MGP cause Keutel syndrome, leading to ectopic abnormal calcification and midfacial hypoplasia." (PMID 19712474, 2009). "Forty-two cases of Keutel syndrome have been reported until now, where only 30% of them were genotyped for MGP, by which eight different loss-of-function mutations were identified in the MGP gene." (PMID 35054981, 2022). "Keutel syndrome (KS) is a rare autosomal recessive genetic disorder that was first identified in the beginning of the 1970s and nearly 30 years later attributed to loss-of-function mutations in the gene coding for the matrix Gla protein (MGP)." (PMID 33996798, 2021). "Moreover, Keutel syndrome, a rare autosomal inherited condition characterized by enhanced chondrogenesis, is caused by mutations in the MGP gene." (PMID 30717170, 2019). "Interestingly, mutations in this gene coding for MGP can cause Keutel syndrome (KS) in human patients, leading to ectopic abnormal calcification and midfacial hypoplasia, which substantiates the role of MGP in extracellular matrix (ECM) calcification regulation." (PMID 32405535, 2020). "Keutel syndrome (KS; OMIM # 245150) is an extremely rare autosomal recessive disorder caused by loss-of-function mutations in the MGP gene." (PMID 31052252, 2019). "Keutel syndrome, a rare autosomal recessive disease, stems from mutations in the gene Matrix GLA Protein (MGP), and these patients develop ectopic calcification in soft tissue throughout the body, including the vasculature." (PMID 29632866, 2018). "After biallelic GGCX mutations were identified in this patient, functional analysis showed an abolished carboxylation of MGP, which remained in the inactive state, thus mimicking part of the Keutel syndrome phenotype." (PMID 28125048, 2017). "Brachytelephalangy of the fingers is a distinct characteristic of Keutel syndrome (OMIM#245150), an autosomal recessive disorder caused by mutations in MGP, a VKDP that is carboxylated by GGCX." (PMID 28125048, 2017). "As can be learned from PXE, PXE-like syndrome and Keutel's syndrome, MGP and the vitamin K cycle are among the most important known regulators of calcification and VSMC phenotype switching." (PMID 23248645, 2012). "For example, the matrix Gla protein (MGP) is a vitamin K-dependent protein present in the extracellular matrix and a well-documented inhibitor of ectopic mineralization, whose dysfunction is associated with the development of Keutel syndrome." (PMID 36834795, 2023). "Although MGP knockout mice show severe arterial calcification early in their life, vascular calcification usually does not appear in patients with Keutel syndrome accompanying loss of function mutation in the MGP gene." (PMID 39086959, 2022). "Despite the craniofacial phenotype of the Keutel syndrome patients and the analogous mouse models, the exact mechanism of MGP’s action in the regulation of craniofacial development is still unknown." (PMID 34205668, 2021). "This could help explain why many tissues that contain MGP synthesizing cells do not become calcified in MGP knockout animals and in Keutel syndrome, a human disease characterized by loss of MGP function." (PMID 25210519, 2014). "The GGCX mutation results in decreased activity of MGP and subsequently an impaired inhibitory potential for calcification, similar to the situation in Keutel's syndrome in which MGP is absent." (PMID 23248645, 2012).
calcification (29 papers, 2009 to 2025). Process by which organic tissue becomes hardened by the physiologic deposit of calcium salts. "There is evidence that the inactive form of MGP reflects vitamin K-deficiency as a result of warfarin treatment, and this is associated with medial arterial calcification in HD patients." (PMID 34289653, 2021). "Herrmann and colleagues identified 8 MGP polymorphisms and found that individuals with femoral atherosclerotic plaques calcifications and myocardial infarction were more frequently carriers of the minor A allele of rs1800801." (PMID 32584873, 2020). "Aim of this review is to present the pathophysiologic mechanisms underlying the activation and function of MGP and review the existing, accumulating data regarding the association between vitamin K, MGP and vascular calcification/CV disease in CKD patients." (PMID 32391368, 2020). "Recently, our studies revealed a significant contribution of EndMTs in vascular calcification caused by deficiency of Matrix Gla protein (MGP), a well-established model of vascular calcification." (PMID 27936229, 2016). "Since matrix Gla protein is considered a potent inhibitor of vascular calcification, it is speculated that THs may prevent vascular calcification associated with atherosclerotic plaque progression." (PMID 41451128, 2025). "Arterial calcifications caused by MGP-deficiency were originally shown in MGP-null mice in 1997." (PMID 33119722, 2020). "Therefore, we conducted this meta-analysis in order to precisely elucidate the genetic roles for the MGP gene rs1800801, rs1800802, rs4236 polymorphisms in the process of vascular calcification and atherosclerotic disease." (PMID 28821877, 2017). "Over the past decade, increasing evidence has indicated that several single nucleotide polymorphisms (SNPs) of the MGP gene may play a crucial role in the susceptibility of vascular calcification and atherosclerotic disease." (PMID 28821877, 2017). "Many studies have analyzed the effect of SNP of the MGP gene on arterial calcification, but most of them focusing on coronary calcifications, which is a surrogate marker of coronary atheroma plaque presence." (PMID 38186884, 2024). "Vitamin K has a role in reducing the level of vascular and valvular calcifications through the activation of vitamin K-dependent proteins, such as MGP." (PMID 39857632, 2024). "In this aspect, different functional forms of MGP are being thoroughly investigated as predictive and prognostic candidate biomarkers and as a therapeutic target for the treatment of vascular calcification and CVD." (PMID 38542487, 2024). "Vascular calcification contributes to the pathogenesis of coronary artery disease while matrix Gla protein (MGP) was recently identified as a potent inhibitor of vascular calcification." (PMID 33669806, 2021). "Furthermore, warfarin inhibits the vitamin K-dependent gamma-glutamyl carboxylation of proteins, including matrix Gla protein and osteocalcin (bone Gla protein); therefore, the use of warfarin may increase the risk of vascular calcification and osteoporotic bone fracture in diabetic AF patients." (PMID 32156277, 2020). "Animals treated with warfarin exhibited accelerated aortic calcification due to a 5-fold downregulation of circulating MGP." (PMID 32391368, 2020). "Recent studies further proved that high levels of inactive MGP, also known as uncarboxylated MGP (ucMGP), were significantly correlated with vascular medial calcification in patients with CKD." (PMID 33585452, 2020). "In the present study, we investigated MGP and vitamin K status in age-matched HDpatients and healthy controls; in addition, we assessed vascular calcification and CVD in HDpatients." (PMID 31538831, 2019). "MGP serves as an inhibitor of cardiovascular calcification as observed in MGP null mice and arterial and valvular calcification after warfarin intake." (PMID 19712474, 2009).